PTH (parathyroid hormone)
Diseases named in the same sentence as PTH in open-access papers (continued):
Sharing a sentence is not in itself a finding about the gene and the disease.
Hypomagnesemia (continued). "Our results indicate that the higher prevalence of hypercalcemic crisis persisted after adjusting for eGFR and PTH levels in patients with hypomagnesemia." (PMID 34416890, 2021). "In contrast, patients with hypomagnesemia had a higher mean serum calcium and parathyroid hormone than individuals with normal magnesium." (PMID 34416890, 2021). "Severe hypomagnesemia decreases PTH secretion and increases resistance to PTH effects in bone and kidney." (PMID 29694629, 2018). "Parathyroid hormone (PTH) and magnesium are of particular interest in this context, as elevated levels of PTH and hypomagnesemia have been reported together with MS." (PMID 19187564, 2009). "Hypomagnesemia not only inhibits PTH secretion but may also reduce target organ sensitivity to circulating PTH, resulting in biochemical characteristics similar to primary hypoparathyroidism." (PMID 41601788, 2026). "However, the efficiency of the calcium regulatory system in transition cows is dependent on factors, such as hypomagnesemia and metabolic alkalosis that lead to reduced parathyroid hormone (PTH) receptor sensitivity and delayed calcium regulatory responses." (PMID 40860924, 2025). "Laboratory tests revealed hypomagnesemia and elevated parathyroid hormone levels." (PMID 40826740, 2025). "Furthermore, patients with severe infection often suffer from hypomagnesemia, which suppresses the secretion of parathyroid hormone." (PMID 38903514, 2024). "Immunoreactive PTH levels are normal or low in most hypomagnesemia-hypocalcemic individuals." (PMID 36589976, 2022). "Conclusions and Clinical Importance: Hypomagnesemia may contribute to alterations in iCa and parathyroid hormone in dogs with CE +/‐ PLE and decreased 25(OH)D." (PMID 36214464, 2022). "Interestingly, hypomagnesemia can also block PTH synthesis and secretion by increasing the activity of the inhibitory G-alpha subunit." (PMID 36382754, 2022). "Whilst low levels of magnesium are known to stimulate PTH secretion by activation of the calcium-sensing receptor, only severe hypomagnesemia with serum magnesium < 0.5 mmol/l and an intracellular magnesium deficit is supposed to induce a paradoxical block of PTH secretion." (PMID 36190530, 2022). "Our findings revealed that hypomagnesemia was associated with lower hemoglobin levels, independent of age, sex, disease duration, BMI, albumin, calcium, eGFR, and PTH in PHPT patients." (PMID 34873402, 2021). "Hypomagnesemia is associated with lower hemoglobin, independent of albumin, calcium, eGFR, and PTH in PHPT patients." (PMID 34873402, 2021). "Hypomagnesemia may limit secretion of and end-organ responsiveness to PTH,18,19 but [Mg]s was also normal." (PMID 27081654, 2016). "Indeed, hypomagnesemia affects the secretion and activity of PTH as well as tissue sensitivity to PTH and reduces the activity of the 25-hydroxycholecalciferol-1-hydroxylase, hence resulting in low serum concentrations of 1,25(OH)2D." (PMID 26273297, 2015). "Hypomagnesemia may thus contribute to the lower PTH levels observed in smokers." (PMID 31765401, 2019). "However, this fact could be attributed to the hypomagnesemia detected in this patient, since chronically reduced magnesium levels inhibit PTH secretion." (PMID 11836550, 2002). "Regarding the regulation of calcium (Ca) and phosphorus (P) homeostasis: parathyroid hormone (PTH) secretion is triggered by low serum calcium levels and inhibited by hypomagnesemia and elevated 1,25(OH)2D3 levels." (PMID 40284243, 2025). "Mg is essential for the functioning of parathyroid hormone (PTH) and vitamin D. Hypomagnesemia during postmenopause needs to be monitored together with the status of those minerals closely related to phosphorus-calcium metabolism, in order to optimize homeostatic equilibrium and bone health." (PMID 32751522, 2020).
Hypomagnesemia (continued). "The lack of PTH effect itself may contribute to hypomagnesemia because PTH increases the resorption of magnesium in the distal renal tubule, but other causes of chronic hypomagnesemia should always be investigated." (PMID 36382754, 2022). "Other limitations include variation in measurement method of PTH levels and non-availability of data on serum magnesium levels (hypomagnesemia) that may influence serum PTH levels." (PMID 32704281, 2020).
Osteopenia (105 papers, 2009 to 2026). Osteopenia is a term to define bone density that is not normal but also not as low as osteoporosis. "In the control group, OP was positively associated with calcitonin (B = 0.923, p = 0.021), while osteopenia correlated positively with PTH (B = 0.061, p = 0.001)." (PMID 40428747, 2025). "Patients with osteopenia are found to have sometimes a high level of PTH as a part of the pathological mechanism that causes bone thinning." (PMID 38740674, 2024). "Simple VD deficiency or slight PTH increase can’t be used as the diagnostic basis for osteopenia in perimenopausal women of this region." (PMID 28686649, 2017). "In both univariate and multivariate analysis, increased age, PMH of fracture and increased PTH were identified to be positively associated with the presence of OP and/or osteopenia in RA patients." (PMID 25886059, 2015). "In CKD patients, low serum 1,25-dihydroxyvitamin D triggers higher secretion of PTH, which precipitates high bone turnover and exacerbates osteopenia and finally results in bone loss." (PMID 24752599, 2014). "Low serum 1,25-dihydroxyvitamin D triggers higher levels of serum PTH, which in turn promotes high bone turnover, exacerbates osteopenia and finally results in cortical bone loss and pathogenesis of osteoporosis." (PMID 24752599, 2014). "High PTH levels are a potential cause of osteopenia and were observed in patients with SLE." (PMID 38069267, 2023). "Histomorphometric and micro-CT evaluations for the contralateral tibiae demonstrated that continuous PTH1–34 infusion for two weeks caused osteopenia, and intermittent administration increased the bone mass, although bone formation and resorption were enhanced in both PTH-treated groups." (PMID 30181648, 2018). "In conclusion, our study showed that TAC-induced heart failure leads to cortical bone osteopenia in a PTH- and FGF23-independent manner in mice." (PMID 41515999, 2025). "A 4-week PTH screen showed good discrimination for radiologic osteopenia (AUC 0.78), supporting its role within structured bone health care." (PMID 41378196, 2025). "The lowest mean PTH value was noted in the group with osteopenia (20.41 ± 13.23 pg/mL), which is also in the reference range of PTH levels (14–72 pg/mL)." (PMID 40149488, 2025). "ROC analysis demonstrated good discrimination of radiologic osteopenia by PTH, with an area under the curve (AUC) of 0.784 (95% CI: 0.715–0.852; p < 0.001)." (PMID 41378196, 2025). "MBD was defined as PTH >18 pmol/L at 4 weeks; ROC against radiographic osteopenia showed good discrimination (AUC 0.78)." (PMID 41378196, 2025). "IL-1β is known to be a potent stimulator of bone resorption and has been shown to synergize with PTH in promoting osteopenia in fetal rat long-bone cultures, even when both are used at very low concentrations." (PMID 41341029, 2025). "The osteopenia in TAC mice was associated with a site-specific, PTH-independent upregulation in osteoclastic bone resorption." (PMID 41515999, 2025). "The PTH levels were significantly higher in osteopenia and PMOP patients than in NC subjects (P < 0.05, P < 0.01, respectively)." (PMID 35083231, 2021). "Osteopenia and osteoporotic patients had higher serum levels of PTH, this was statistically significant for the Total BMD (P = 0.008) and Hip BMD (P = 0.019)." (PMID 33180791, 2020). "In other words, should we insist on correcting PTH levels in patients whose life expectancy is short or where end-organ damage (diffuse vascular calcifications or severe osteopenia) is already present?" (PMID 32075103, 2020). "A study suggested that a high level of parathyroid hormone plays a role in the pathophysiological process of osteopenia in patients with depressive disorders." (PMID 29641581, 2018).
Osteopenia (continued). "In the fully adjusted model, after being adjusted for age, weight, height, diabetic duration, and serum concentrations of Cr, Ca, vitD3, and PTH, when compared with the patients in T1, the odds for at least osteopenia were 17% lower in T2 and 46% lower in T3." (PMID 27022396, 2016). "When PTH levels increase, they promote bone resorption, and persistently high PTH concentrations, as documented in CKD patients, eventually lead to, osteopenia, and increased risk of pathological fractures." (PMID 25333360, 2014). "Two osteopenic models included Ovx and peak lactating rats whereas the recovery model was obtained by PTH treatment to Ovx rats after osteopenia was established." (PMID 24386209, 2013). "Ovx rats with established osteopenia were administered with PTH (parathyroid hormone, trabecular restoration group), and restoration was allowed to become comparable to sham Ovx (control) group using bone mineral density (BMD) and μCT determinants." (PMID 24386209, 2013). "It is noteworthy that the extent of reduction in bound water in the Ovx+PTH group was comparable to lactating rats (physiological osteopenia that is normally reversed after weaning), suggesting that greater loss in bound water could be a precondition for reversal of osteopenia." (PMID 24386209, 2013). "Elevated PTH in osteopenia have been found to increase the incidence of HF particularly in males." (PMID 38740674, 2024). "The relationship between osteopenia and low serum calcium levels may stem from the stimulation of PTH in preterm neonates." (PMID 39866582, 2024). "The comprehensive diagnosis of MBD primarily relies on features such as decreased serum calcium and phosphorus levels, elevated serum ALP and parathyroid hormone (PTH) levels, as well as characteristics observed in X-ray imaging indicative of osteopenia or fractures." (PMID 38255389, 2024). "In addition, some animal studies also confirmed the beneficial effects of combination therapy on promoting implant fixation, preventing disuse-induced osteopenia, and improving posterior lumbar vertebral fusion, compared with PTH or ZOL monotherapy." (PMID 35546997, 2022). "Hence, increased osteoblast apoptosis is at least partially responsible for the decreased bone formation associated with the osteopenia induced by glucocorticoid excess, and conversely, inhibition of osteoblast apoptosis might contribute to the anabolic effect of intermittent administration of PTH." (PMID 27409635, 2016). "They speculate that these patients often exhibit osteopenia and lower than normal PTH levels with a net result: the preservation of normal serum calcium levels." (PMID 19727413, 2009). "Additionally, osteopenia in the control group was significantly influenced by estrogen (B = −0.139, p = 0.003, negative correlation), calcitonin (B = 1.021, p = 0.006, positive correlation), and PTH (B = 0.108, p < 0.001, positive correlation)." (PMID 40428747, 2025). "Furthermore, we found that for the osteopenia group, greater vitamin D levels were associated with greater femoral neck BMD (p = 0.020) and total hip BMD (p = 0.008) and lower β-CTX (p < 0.001), OC (p < 0.001), and PTH (p < 0.001)." (PMID 38268673, 2024). "Of these, two had insufficient serum levels of hydroxy-vitamin D, abnormal (high/low) parathyroid hormone levels but normal bone mineralization, while the third patient had normal serum levels of hydroxy-vitamin D and parathyroid hormone but was diagnosed with femoral osteopenia." (PMID 27169468, 2016). "A 4-week PTH screen, interpreted with ALP, showed good discrimination for radiologic osteopenia (AUC 0.78)." (PMID 41378196, 2025). "Bone loss in mouse models of ovariectomy, continuous parathyroid hormone (PTH) infusion, or RANKL-induced osteopenia was also significantly improved in Nlrp3−/− mice [86•]." (PMID 35567665, 2022). "Among bone turnover markers, PTH and RANKL showed significant differences between control and osteopenia groups." (PMID 33376557, 2020).
Osteopenia (continued). "The levels of bone turnover markers, PTH, and RANKL were found to be significantly different between control and the osteopenia group." (PMID 33376557, 2020). "In conclusion, the study shows for the first time that PTH and ABL has very similar efficacy in preventing disuse osteopenia in immobilized rats when given in the same molar concentration." (PMID 33162940, 2020). "Before the development of cinacalcet, vitamin D compounds were the mainstay of therapy to normalize perturbed PTH concentrations in CKD, which if left unchecked lead to painful fractures, bone deformity, and generalized osteopenia." (PMID 23637579, 2013). "Although our data do not provide a final mechanistic explanation for these observations, we could exclude PTH and FGF23 as hormonal mediators of HF-induced osteopenia." (PMID 41515999, 2025). "Clinical experience showed that total parathyroidectom had disadvantages, such as candidate for kidney transplantation, lifelong substitution therapy, and osteopenia developed in the absence of PTH." (PMID 24886230, 2014). "Patients with CD, with and without osteopenia, were compared before and after oral calcium load showing that serum 1,25 (OH)2D3 plasma levels were higher in subjects with osteopenia than in those without it, likely due to a secondary increase in PTH levels as an effect of hypercortisolism." (PMID 35267948, 2022). "However, no study has yet investigated PTH and abaloparatide in a direct mole-to-mole comparison in prevention of immobilization-induced osteopenia." (PMID 33162940, 2020). "In the absence of skeletal osteoclast resistance to PTH, hyperparathyroid bone disease such as osteopenia or osteitis fibrosa may develop." (PMID 21274302, 2009). "Our data also exclude tissue hypersensitivity (pseudohyperparathyroidism) to PTH postulated as pathogenetic mechanism for the osteopenia, since the secretion of Rankl in osteoblasts from MLII mice was not affected in response to PTH stimulation." (PMID 24127423, 2013).
parathyroid carcinoma (98 papers, 2006 to 2026). "This case stands out due to the high levels of parathyroid hormone, which typically raises suspicion for parathyroid carcinoma, making it a unique diagnostic challenge." (PMID 41783670, 2025). "This is consistent with our finding of expression of variant GCM2 in both familial and sporadic parathyroid carcinoma with increased ability to stimulate PTH transcription." (PMID 35038313, 2022). "The lowest serum calcium level reported in the literature with parathyroid carcinoma has been 12.2 mg/dl, and the lowest reported PTH level associated with parathyroid carcinoma has been 159 pg/ml in conjunction with a serum calcium level of 13.3 mg/dl." (PMID 36188029, 2022). "Patients treated for PHPT caused by parathyroid carcinoma (PC) were excluded, because they showed average calcium and PTH preoperative values higher than patients treated for benign PHPT." (PMID 34671396, 2021). "Parathyroid carcinoma (PC) is an extremely rare disease, typically presenting with marked elevations of serum calcium concentrations and associated with significantly increased parathyroid hormone (PTH) levels." (PMID 39777339, 2024). "A right emithyroidectomy and right superior and inferior parathyroidectomy was performed and histopathological examination showed a parathyroid carcinoma (immunohistochemistry positive for PTH and chromogranin A, Ki-67 10%) associated with follicular hyperplasia." (PMID 22276015, 2009). "As it is difficult to distinguish parathyroid carcinoma from parathyroid hyperplasia (which is the most common cause of SHPT) by routine image diagnosis, cinacalcet might cause a delay in the diagnosis of parathyroid carcinoma when it is used to control the PTH level in chronic dialysis patients." (PMID 29047366, 2017). "Parathyroid carcinoma (PC) is a rare endocrine malignancy characterized by aggressive clinical behavior driven primarily by parathyroid hormone (PTH) overproduction." (PMID 42196524, 2026). "Based on the histopathological findings of the surgical specimen demonstrating clear invasion of tumor cells into the thyroid tissue and positive immunostaining for parathyroid hormone (PTH), a diagnosis of parathyroid carcinoma was established." (PMID 41216108, 2025). "PC is characterized by severe bone loss and increased plasma calcium levels due to excessive parathyroid hormone (PTH) production from the malignant parathyroid tumor." (PMID 40026929, 2025). "Cancer-type patients had a median age of 30.0 years, with median calcium and PTH levels of 12.6 mg/dL and 800.8 pg/mL, respectively, clinically resembling parathyroid cancer." (PMID 40434298, 2025). "As the combination of a young age, elevated calcium and PTH levels, and a large tumor size are key factors for suspicion of parathyroid cancer, this finding demonstrates the potential effectiveness of our clustering model." (PMID 40434298, 2025). "Regular follow-up is essential to monitor for the recurrence of parathyroid carcinoma, including monitoring of calcium and PTH levels every two months for the first five years and annually after that, along with annual cervical ultrasound scans." (PMID 40729208, 2023). "As expected from the data on adults diagnosed with a parathyroid carcinoma, this exceptional histological entity (that is described in less than 1% of pediatric cases with PHP) is associated with very high PTH values." (PMID 37893182, 2023). "Parathyroid carcinoma should be considered in patients presenting with severe symptomatic disease, neck mass, and significantly elevated calcium and PTH levels." (PMID 38046185, 2023). "Laboratorial identification of high values of calcium and PTH should always lead to a suspected diagnosis of parathyroid carcinoma, and for this reason, in bloc resection should be considered." (PMID 37252701, 2023).